H2BN1 (H2B.N variant histone 1)
Description:
Core component of nucleosome. Nucleosomes wrap and compact DNA into chromatin, limiting DNA accessibility to the cellular machineries which require DNA as a template. Histones thereby play a central role in transcription regulation, DNA repair, DNA replication and chromosomal stability. DNA accessibility is regulated via a complex set of post-translational modifications of histones, also called histone code, and nucleosome remodeling.
Synonyms: H2B.N
Tractability: No criterion of Open Targets' tractability assessment is met for any kind of drug.
Gene: Protein-coding gene on chromosome 17 (32,895,433 to 32,906,586, forward strand). Ensembl gene ENSG00000290320.
Subcellular location: Nucleus; Chromosome
Gene Ontology:
Molecular function: DNA binding; protein heterodimerization activity; structural constituent of chromatin
Cellular component: chromosome; nucleosome; nucleus